BRCA1 (BRCA1 DNA repair associated)
Diseases named in the same sentence as BRCA1 in open-access papers (continued):
Sharing a sentence is not in itself a finding about the gene and the disease.
breast cancer (continued). "BRCA1 and BRCA2 pathogenic variants were identified in 12.6% (97/768) of breast cancer patients, whereas, 2.5% (19/768) of the individuals carried a variant in another high risk gene and 9.7% (74/768) in a moderate/low penetrance gene." (PMID 31159747, 2019). "The limitation of our study was the small number of BRCA1- and BRCA2-deficient breast cancers relative to BRCA-proficient breast cancers." (PMID 31022191, 2019). "HCC 1937 breast cancer cells harboring mutant BRCA1 induced oxidative stress and a glycolytic phenotype in co-cultured stromal fibroblasts." (PMID 30691108, 2019). "We conclude that the breast cancer risk association of these two FANCC variants, if any, is much smaller than for BRCA1, BRCA2 or PALB2 mutations." (PMID 31467304, 2019). "Despite being driven by germline mutations in functionally related genes,BRCA1, BRCA2, and PALB2mutated breast cancers constitute a heterogeneous group of tumors at theimmunohistochemical and molecular level." (PMID 31067289, 2019). "Apostolou and Fostira (2013) claimed hereditary and genetic factors including mutations in the BRCA1 and BRCA2 genes and other breast cancer susceptible genes account for 5%–10% of breast cancer cases." (PMID 31759379, 2019). "A recent prospective cohort study has estimated that the cumulative risks of breast cancer to age 80 years was 72% for BRCA1 and 69% for BRCA2 carriers." (PMID 31065452, 2019). "The differences in immunophenotype between BRCA1- and BRCA2-deficient breast cancers can be attributed, in part, to PTEN gene mutation." (PMID 31022191, 2019). "To clarify the BRCA1 L63X founder mutation, we compared the three groups (BRCA1 L63X, other BRCA1 mutations, and BRCA2 mutations) of breast cancer patients." (PMID 31143373, 2019). "There is definite evidence that prostate cancer risk is increased in BRCA1 and BRCA2 mutation carriers ascertained by a family history of breast cancer." (PMID 31477094, 2019). "PARP inhibitors already have proven efficacy as monotherapies for BRCA1-/- advanced breast cancer, and multiple trials are now assessing possible combinations with cell cycle-based chemotherapies for TNBC." (PMID 30720718, 2019). "BRCA1 and BRCA2 germline mutation carriers have an increased risk of breast cancer, but the cellular and molecular basis of this increased risk is still poorly defined." (PMID 31519911, 2019). "We further determined the impact of BRCA1 on breast cancer stemness using the ALDH activity assay as a readout for the endogenous ALDH activities, a widely used functional assay of breast cancer stemness." (PMID 31273285, 2019). "Almost all (96%) respondents (totally) disagreed with the statement ‘I (would) encounter difficulties in discussing the option of BRCA1/2 with young breast cancer patients’." (PMID 30238178, 2019). "It is noteworthy that an on-going clinical trial is investigating pembrolizumab, an anti-PD-1 antibody, in advanced BRCA1- and BRCA2-mutated breast cancer patients (ClinicalTrials.gov identifier: NCT03025035)." (PMID 31022191, 2019). "Previous studies have associated the trinucleotide repeat polymorphism (CAGn) in the exon 1 of the androgen receptor gene (AR) and mutations in BRCA1 and BRCA2 with breast cancer among Filipino women." (PMID 31030479, 2019). "The odds of developing ER + PR+ breast cancer was 2.34 (95% CI = 1.18–4.64) among women with late age at first birth (> 27 years) and unmethylated BRCA1 promoters, whereas among women with methylated BRCA1 the OR was 0.88 (95% CI = 0.51–1.51)." (PMID 31533668, 2019). "The proportion of PTEN mutant samples in BRCA-proficient, and in BRCA1- and BRCA2-deficient breast cancers was 7.9%, 29%, and 5.9%, respectively." (PMID 31022191, 2019). "Missense mutations in BRCA1 (e.g., p.Cys61Gly) has been shown to be capable of distracting the BARD1/BRCA1 interaction, thus leading to breast cancer." (PMID 30975222, 2019).
breast cancer (continued). "This is also the same axis that has been targeted to inhibit/prevent basal‐like BRCA1 breast cancer." (PMID 31267556, 2019). "Advances in molecular biology in recent decades have resulted in the identification of genes, such as the tumor suppressor genes BRCA1 and BRCA2, that, when altered, significantly increase the risk of developing breast cancer, ovarian cancer, and other tumors." (PMID 31244284, 2019). "In multivariable multinomial models including all tumor characteristics that were significantly different between non‐BRCA and BRCA1‐positive breast cancer patients, only ER‐negativity remained significant (ORBRCA1 vs non‐BRCA: 5.19 [2.68–10.06])." (PMID 30175445, 2019). "While BRCA1 carriers frequently develop triple-negative, basal-like, aggressive breast tumors, hormone signaling is important in the genesis of BRCA1 mutant breast cancers." (PMID 31771627, 2019). "In agreement with the National Comprehensive Cancer Network (NCCN) guidelines, our data also warrant BRCA1/2 testing in families with male breast cancer (NCCN Guidelines Version 2.2019)." (PMID 31528241, 2019). "Family history of breast cancer, inherited BRCA1 and/or BRCA2 mutations, alcohol intake, and exogenous hormone intake are known risk factors underlying the elevated incidence rate of breast cancer." (PMID 31817161, 2019). "Patients with BRCA1 and BRCA2 mutations have up to an 87 per cent lifetime risk of developing breast cancer." (PMID 30957063, 2019). "BRCA1 carriers were more likely to have a personal history of another malignant cancer in addition to their breast cancer than patients with non‐BRCA patients (ORBRCA1 vs non‐BRCA: 2.93 [1.37–6.27])." (PMID 30175445, 2019). "Inactivation of BRCA1 (breast cancer and ovarian cancer-specific tumor suppressor protein) by mutations or promoter methylation has been shown to be associated with upregulated PARP1." (PMID 31856867, 2019). "It is possible that members of the FA core complex that act upstream of HRR are less relevant for breast cancer due to their more specialized function in the repair of crosslinks while BRCA1, BRCA2, and PALB2 function more globally at DNA double-strand breaks." (PMID 31467304, 2019). "Sixty-eight percent of breast cancers occurring in BRCA1 carriers were triple-negative, compared to only 16% of breast cancers in BRCA2 carriers." (PMID 30980249, 2019). "PDTCs derived from this tumour were sensitive to chlorambucil, which supports our results obtained with the Brca1‐deleted mouse mammary tumour‐derived cells, upon REV7 depletion using shRNAs." (PMID 31273933, 2019). "In 55 patients with history of familial breast cancer, the founder BRCA1 ex9–12del was identified in two samples and a third sample with familial history showed a BRCA1 ex12deletion." (PMID 30630528, 2019). "In breast cancer cells, PTEN inhibition represses nuclear translocation of breast cancer susceptibility 1 (BRCA1) and Rad51; this impairs DNA repair resulting in an accumulation of damaged DNA, which contributes to cell senescence." (PMID 30521029, 2019). "Thirty‐eight percent of BRCA1/2 carriers were identified through selective clinical testing of 8.2% of breast cancer patients." (PMID 30175445, 2019). "The proportion of BRCA1- and BRCA2-deficient breast cancers was also significantly higher in WSI compared to TCGA." (PMID 31022191, 2019). "This suggests that different mechanisms of resistance to PARP inhibition must exist in these genetically distinct mouse models, with important clinical implications if such differences were replicated in BRCA1- and BRCA2-mutated human breast cancers." (PMID 31080552, 2019). "Due to the close proximity of the BRCA1 (breast cancer 1, early onset) and the BECN1 gene at the 17q21 chromosome, it was postulated that BECN1 deletions are rather a passenger event." (PMID 31877888, 2019).
breast cancer (continued). "Women at high‐risk for breast cancer include those with inherited mutations in the BRCA1 or BRCA2 genes and have a ~ 72 and ~ 69% lifetime risk of developing breast cancer by the age of 80, respectively." (PMID 31267556, 2019). "One study reported that PI3K/AKT activation induced the upregulation of BRCA1 in tamoxifen-resistant breast cancer cells and resensitized them to CDDP treatment." (PMID 30927924, 2019). "Surprisingly, hypoxia has much stronger protective effects in the stemness of BRCA1-competent breast cancer cells." (PMID 31273285, 2019). "While the frequency of pathogenic variants in BRCA1 and BRCA2 is high in the Ashkenazi Jewish population, it was found that 0.3% of all Ashkenazi Jewish breast cancer patients were double heterozygotes for BRCA1/2 pathogenic variants." (PMID 31395037, 2019). "From these data, we suggest that CTSS inhibition is a good strategy for functional restoration of BRCA1 in breast cancers with reduced BRCA1 protein stability." (PMID 30006610, 2019). "While most breast cancers carrying BRCA1 mutations undergo loss-of-heterozygosity (LOH) of their wild-type allele as their second hit, BRCA1 and BRCA2 promoter methylation have also been detected in some tumors without LOH." (PMID 31225507, 2019). "For instance, themes of DNA repair and G2‐M checkpoint regulation are consistent with the known roles of BRCA1/BRCA2 and ATM proteins, which are established risk factors for breast cancer." (PMID 30872331, 2019). "The studies are difficult to compare due to differences in methodology and patient populations as well as different prognoses of breast cancers with BRCA1 vs. BRCA2 alterations." (PMID 31346352, 2019). "We thank Florentine S. Hilbers for sharing the Whole Exome Sequencing data of the non-BRCA1/2 breast cancer pedigrees." (PMID 31214250, 2019). "Nonetheless, much higher ALDH+ populations were observed in the siBRCA1-treated SKBR3, which further supports BRCA1 as an important regulator of breast cancer cell stemness." (PMID 31273285, 2019). "According to a Dutch study, the overall 10-year contralateral breast cancer risk for unselected BRCA1 or BRCA2 mutation carriers is approximately 18%, whereas that for mutation carriers with a family history of breast cancer is higher, at 25%." (PMID 30980249, 2019). "Apart from BRCA1 and BRCA2, the rarely mutated breast cancer predisposition genes PALB2 and FANCM have been associated with TNBC." (PMID 31683572, 2019). "The benefit of red wine intake to some women with breast cancer was evident in observational studies and was attributed to the binding of resveratrol to the oestrogen receptor, which promotes BRCA1 and BRCA2 protein transcription." (PMID 31505792, 2019). "Emerging experimental and epidemiologic data strongly implicate progesterone-mediated RANK signaling in BRCA1-breast cancer development." (PMID 31069010, 2019). "BRCA1- and BRCA2-deficient breast cancers from WSI had 0.60 and 0.41 median proportion of signature 3 compared to median of 0 in BRCA-proficient breast cancers (P = 2.2 x 10−28 and 1.9 x 10−16, respectively)." (PMID 31022191, 2019). "Of the 5,099 breast cancer patients, 92 (1.8%) were identified as BRCA1/2 carriers (50 BRCA1 carriers and 42 BRCA2 carriers) and 5,007 were non‐BRCA." (PMID 30175445, 2019). "BReast Cancer Associated proteins 1 and 2 (BRCA1, −2) and Partner and Localizer of BRCA2 (PALB2) protein are tumour suppressors linked to a spectrum of malignancies, including breast cancer and Fanconi anemia." (PMID 31017574, 2019).
breast cancer (continued). "We used extreme phenotype sampling to recruit 133 BRCA1-positive patients with either early breast cancer onset, below 35 (early AAO cohort) or cancer-free by age 60 (controls)." (PMID 31395037, 2019). "We offered a simplified and streamlined BRCA1/2 testing protocol to unselected breast cancer patients." (PMID 30311024, 2019). "Recently, Green and colleagues reported that low BRCA1 expression was associated with high numbers of CD8+ TILs and poor survival in patients with breast cancer." (PMID 31023256, 2019). "BRCA1 and BRCA2 mutation patients had a respective 4.5- and 3.4-fold elevated risk of developing contralateral breast cancer." (PMID 31998630, 2019). "The DNA- associated proteins BRCA1 and BRCA2 (Breast Cancer 1 and 2) also play an important role in DNA break repair and recombination in association with PALB2 (Partner and Localizer of BRCA2)." (PMID 30995915, 2019). "To exclude the possibility that these observations were cell model dependent, we tested the response to IFN in isogenic BRCA1 mutated breast cancer cells and cells stably transfected with BRCA1 (HCC1937+ BRCA1)." (PMID 31840082, 2019). "BLBC accounts for up to 15% of breast tumors and is commonly diagnosed in pre-menopausal women under the age of 40, women of African descent, and carriers with defects in the familial breast cancer gene, BRCA1." (PMID 30720718, 2019). "On the other hand, down-regulation of BRCA1 in SKBR3 breast cancer cells significantly increased the CSC-like populations." (PMID 31273285, 2019). "In this study, we investigated the features of genomic instability, expression of checkpoint molecules, and T cell-inflamed signature stratified by BRCA1- and BRCA2-deficiency status in two large series of breast cancer patients." (PMID 31022191, 2019). "Surprisingly, hypoxia preferentially blocks HDAC inhibitor-induced differentiation of the BRCA1-reconstituted breast cancer cells." (PMID 31273285, 2019). "This suggests an adaptive response of the body to increased ROS production in BRCA1+ patients with breast cancer." (PMID 31597313, 2019). "In parallel, although BRCA1/2 constitutes a well-established genomic biomarker for the development of breast cancer, BRCA1/2 genetic testing is considered medically necessary and, thus, uniquely covered for individuals with a family history of such a disease." (PMID 31427963, 2019). "Besides being of theoretical interest to explain the phenomenon that a few path_BRCA1 variants are frequent, the later onset of breast cancer associated with the most frequent path_BRCA1 variants may be of interest for carriers who have to decide if and when to select prophylactic mastectomy." (PMID 30678073, 2019). "A 2014 phase I study showed that BRCA1/2 breast cancer patients had a 71% response rate (12/17 patients) to olaparib (50 mg BID) and cisplatin (60 mg/m2) combination therapy." (PMID 30934991, 2019). "The BRCA1-delta11q splice variant, which lacks the majority of exon 11 of BRCA1 and consequently bypasses the inactivating germline mutations in this specific exon, promoted resistance to PARP inhibitors and cisplatin in breast cancers." (PMID 31134126, 2019). "In this report, we analyzed Mexican population data from a sample of 3985 outbred individuals, and additional 66 hereditary breast cancer patients were analyzed in order to better define the spectrum of common genomic variation of the BRCA1 and BRCA2 genes." (PMID 30630528, 2019). "BRCA1 and BRCA2 germline mutations have been shown to play a significant role in genetic predisposition to breast cancer." (PMID 31131559, 2019).
breast cancer (continued). "More studies with a larger sample size are warranted to further examine how the different molecular subtypes of breast cancer affect the interaction of BRCA1 and CCND1 with T cell activation in patient survival." (PMID 31023256, 2019). "Hereditary and genetic factors including mutations in the BRCA1 and BRCA2 genes and other breast cancer susceptible genes account for 5%–10% of breast cancer cases." (PMID 31759379, 2019). "Harmful mutations in the BRCA1 and BRCA2 genes can produce very high rates of breast and ovarian cancer and increases the risk of developing breast cancer by up to 85% and the ovarian cancer by up to 54%." (PMID 30898109, 2019). "Inhibition of BRCA1 and BRCA2 gene expression suggested a synergistic cytotoxic effect with PARP1 inhibitor based on previous findings in breast cancer with mutation of BRCA1 or BRCA2." (PMID 30719229, 2019). "Later, BOADICEA model was updated using data from two UK breast cancer studies and family data from BRCA1/2 carriers." (PMID 31839883, 2019). "The proband in this family (III:3) was originally referred for genetic testing of BRCA1/2 because of a strong family history of breast cancer, even though she was unaffected at the time of testing at the age of 40." (PMID 31159747, 2019). "In the five breast cancer patients with BRCA1 LGRs, the most common tumor type was invasive ductal carcinoma." (PMID 31174498, 2019). "Due to the strong association between BRCA mutations and early-onset breast carcinogenesis, genetic testing for BRCA1 and BRCA2 mutations has been suggested for individuals with breast cancer under the age of 60." (PMID 31775907, 2019). "When BRCA1/BRCA2 mutation carriers were diagnosed before age 40 years, the risk of a contralateral breast cancer (CBC) reached nearly 50% in the ensuing 25 years." (PMID 30652428, 2019). "SUMOylation has been shown to regulate transcription factor activities that are involved in several cellular signaling pathways, such as: BRCA1, cell cycle, and steroid hormones in breast cancer pathogenesis." (PMID 33860286, 2019). "Genetic linkage studies have identified BRCA1 (OMIM# 113705) and BRCA2 (OMIM# 600185) as two major genes associated with hereditary breast cancer and high breast cancer risk." (PMID 31131559, 2019). "The BRCA1 protein is a pluripotent regulator of cellular functions in breast cancer, including DNA double‐strand break repair, cell cycle control, transcriptional regulation, ubiquitination, apoptosis and resistance to anticancer agents." (PMID 30714292, 2019). "In unselected TNBC cases, the prevalence of pathogenic germline BRCA1 and BRCA2 mutations is approximately twice as high as in breast cancer overall." (PMID 31683572, 2019). "Advances in WGS analysis and interpretation have revealed rearrangement signatures in breast cancer relating to disease stage, homologous recombination deficiency (HRD), and BRCA1/BRCA2 defects based on size and type of structural variant." (PMID 31748536, 2019). "The features genomic instability observed in both BRCA1- and BRCA2-deficient breast cancers suggests that these cancers would demonstrate similar gene expression signatures and immune features." (PMID 31022191, 2019). "In summary, satisfaction with a simplified testing procedure was very high among unselected breast cancer patients undergoing germline BRCA1/2 testing." (PMID 30311024, 2019). "Ectopic expression of BRCA1 resulted in significant decrease of the CSC-like populations in human breast cancer cells whereas down-regulation of BRCA1 resulted in significant increase of the CSC-like population." (PMID 31273285, 2019).